MMP14 (matrix metallopeptidase 14)
Diseases named in the same sentence as MMP14 in open-access papers (continued):
Sharing a sentence is not in itself a finding about the gene and the disease.
cancer (continued). "In our study, we found that three MMP family members (MMP2, MMP7 and MMP14) which had been verified to induce EMT progression in different types of cancer were decreased in two KIAA1199 knockdown GC cells." (PMID 28422983, 2017). "High expression of MMP-14 on the surface of cancer cells is facilitated by Src and FAK kinases that suppress the endocytic machinery." (PMID 28938563, 2017). "Matrix metalloproteinases (MMPs), including MMP2, MMP9 and MTI-MMP (MMP14), are critical mediators within invadopodia that promote cancer cell invasion." (PMID 28436416, 2017). "Since active MMP-14 is localized on the cell surface, it is amenable to antibody-mediated blockade in cancer, and here we describe our efforts to develop novel inhibitory anti-MMP-14 antibodies." (PMID 28938563, 2017). "The combination of specific inhibitors of Src or FAK with MMP14 can be of therapeutic importance in a cancer that is overdue new treatments." (PMID 26001294, 2017). "MMP-14, also known as membrane-type 1 MMP (MT1-MMP), plays an important role in the invasion and metastasis of a variety of cancers by activation of pro-MMP-2 and ECM degradation." (PMID 28538838, 2017). "The high levels of MMP-14 on the surface of metastatic cancer cells make it an excellent target for cancer therapy development." (PMID 28938563, 2017). "Despite the prominent role of MMP-14 in driving cancer growth and aggression, the mechanisms by which MMP-14 are regulated remain poorly described." (PMID 27531896, 2016). "The data presented herein not only provide a plausible and convincing explanation for how IL-6 increases MMP-14 in cancer to drive metastasis, but implications of this research can be extended into multiple other fields of study." (PMID 27531896, 2016). "When CD44 and MMP-14 are co-expressed in various cancer cell lines, they stimulate cell migration after the soluble part of CD44 is shed from the cell surface." (PMID 27590006, 2016). "Of all MMPs, MT1-MMP (also known as MMP14) appears to have the most significant role in cancer cell migration and invasion into the ECM, likely through its diversity of substrates." (PMID 27802184, 2016). "Highly expressed at the plasma membrane of cancer cells, MMP-14 activates collagenases leading to degradation of the ECM and is specifically linked to cell invasiveness." (PMID 26912656, 2016). "MMP14 has been shown to play a critical role in cancer invasion by inducing ECM degradation and increasing the secretion of other MMPs such as pro-MMP2." (PMID 27564100, 2016). "Our data highlight a functional role for interleukin-6 in cancer dissemination via MMP-14 and pose a new rationale for therapeutically targeting the IL-6 signaling pathway in cancer." (PMID 27531896, 2016). "In particular, MMP2, MMP9 and MMP14 have all been shown to promote cancer progression due to their ability to degrade basement membrane components." (PMID 27789576, 2016). "Previous reports have postulated that E2F and Ets families of transcription factors play a role in cancer through regulation of MMP14 gene promoter activity." (PMID 26850053, 2016). "MMP1 and MMP14 have been reported to induce cancer cell invasion, and MMP14 is further recognized in the activation of MMP2 and MMP9." (PMID 26981862, 2016). "The next challenge is to find out how MMP14 regulates the number of collagen fibres in mature tendons and other tissues, and how defects in this enzyme can lead to cancer and other diseases." (PMID 26390284, 2015). "Recent studies indicated that higher expression of MMP-14 is related to poorer prognosis and shorter survival time in patients with some types of cancer." (PMID 26314845, 2015). "Some cancer cells exploit MMP14 to enable them to leave their tissue of origin and spread around the body." (PMID 26390284, 2015).
cancer (continued). "We then examined the influence of EGF on MMP9 transcription as well as on the transcription of additional MMPs (MMP-1, MMP-2, MMP-3, MMP-7, MMP-10, MMP-13, MMP14, MMP15) and of CD44, a cell adhesion glycoprotein implicated in EMT and cancer metastasis." (PMID 26084289, 2015). "ChIP assay further revealed the decreased binding of Sp1 on MMP-14 promoter in cancer cells treated with sub-cytotoxic MJ." (PMID 23394613, 2013). "Previous studies have revealed the critical role of transcription factor Sp1 in the regulation of MMP-14 expression in cancer cells." (PMID 23394613, 2013). "Analyses using the miRanda and Pic Tar algorithms indicated that several cancer-associated genes including MMP11, ERBB2, ERBB3, EDN1, VEGF-A, MMP14 and BCL-9L, were potential target genes of miR-125a." (PMID 22768249, 2012). "MT1-MMP (MMP14) has emerged as an important collagenase that cancer cells use to degrade and invade in a collagen-rich environment." (PMID 22822400, 2012). "In Oncomine database there are several cancer studies in which MMP14 was found up-regulated such as ovarian, breast and colon but no MM data sets have been recorded." (PMID 19753302, 2009). "GEO database records about three hundred gene expression cancer profiling studies in which MMP14 results to be up-regulated and frequently related to cancer progression." (PMID 19753302, 2009). "Particular MMPs (including MMP-2, MMP-9 and MMP-14) are involved in key events in cancer cells, including proliferation, apoptosis and angiogenesis." (PMID 17894888, 2007). "The selective pressure in ACC—an aggressive cancer with limited treatment options—may have driven particular reliance on the direct DNA repair functions of MMP-14." (PMID 41542511, 2026). "Cancer cells with high replication stress may depend on MMP-14’s nuclear repair function to tolerate ongoing DNA damage." (PMID 41542511, 2026). "Additionally, to enhance the reliability of these results, we employed immunofluorescence methods on a patient sample to observe MMP14 expression in cancer cells." (PMID 40352589, 2025). "Notably, enhanced membrane-bound MMP14 expression promotes cancer cell invasion via cdc42 activation." (PMID 40134439, 2025). "MMP14 is overexpressed in many cancers and is a major upstream activator of other MMPs." (PMID 38661040, 2024). "Furthermore, NKILA also regulates TGFβ signalling and has been shown to decrease MMP14 levels in cancer, resisting cancer migration and metastasis." (PMID 40176927, 2024). "Some authors have suggested that MMP-14 can be used to predict cancer prognosis." (PMID 39125675, 2024). "These included cancer-relevant proteins such as MMP14 and CD14." (PMID 39020428, 2024). "Many TME-related genes (such as VEGFA, MMP14, CCND1, MAP2K1, SLC2A1) and actin cytoskeleton-associated genes (such as ITGB4, ITGA6, ACTG1, VCL) were downregulated, suggesting a less favorable TME and an altered cytoskeleton network in ISO-treated cancer cells." (PMID 38339062, 2024). "Additionally, EphB4 knockout cells had increased expression of matrix metallopeptidase 14, pinin, and keratins 7, 8, 16, and 20, genes associated with increased proliferation, EMT, and metastasis across multiple cancer types." (PMID 39091728, 2024). "Furthermore, miR-150 regulates cancer cell migration by affecting multiple effectors including matrix metalloproteinases (MMP14 and MMP13), cell adhesion molecules (ITGA3, ITGA6), transcription factors (MYB), and epigenetics factors (HMGA2 and EZH2)." (PMID 37924077, 2023). "MMP-14 was shown to promote cancer progression by stimulation of proMMP-2 and degradation of ECM." (PMID 38201481, 2023). "Moreover, certain •NO concentrations modulated the expression of some proteins and enzymesinvolved in cancer cell migration, including, MMP-14, HOX-1, HIF-αas well as EMT-corresponding markers." (PMID 37854626, 2023). "The interaction of UBL3 with MMP14 may be to segregate MMP14 into sEVs to inhibit cancer progression." (PMID 36674743, 2023).
cancer (continued). "These inhibitors work by targeting MMP-14 and preventing its ability to cleave substrates, which could potentially slow down or halt cancer progression." (PMID 37513440, 2023). "MMP14 is a metalloproteinase involved in angiogenesis and cancer invasion." (PMID 37370118, 2023). "MMP14 plays a key role in the early stages of tumor invasion and cancer progression." (PMID 38003931, 2023). "This structure plays a role in cancer invasion by recruiting MMP14 (MT1-MMP) by BSG." (PMID 37823055, 2023). "It should be noted that MMP-14 is also the driving force behind tissue destruction during cancer invasion and metastasis and has a significant effect on intercellular communication, regulating the activity of many plasma membrane-anchored and extracellular proteins." (PMID 37298452, 2023). "MMP14 can be shed into extracellular space from cancer cells." (PMID 35223528, 2022). "However, because pulldown experiments are only semi-quantitative, the impact of the other GalNAc-carrying proteins (MMP-14, β4, β1, and αV integrins) on cancer cell invasion cannot be excluded." (PMID 35028012, 2022). "We also identified several metastasis-associated glycoproteins including MMP-14, EGFR, αV, β1, and β4 integrins that displayed higher levels of the GalNAc glycotope in lectin pull-down samples of highly invasive cancer cell lines, in contrast to poorly invasive cells." (PMID 35028012, 2022). "The increase of several MMPs' expression and enzymatic activity, such as MMP-1, MMP-2, MMP-3, MMP-7, MMP-9, MMP-10, and MMP-14, correlates with the aggressiveness of different types of cancer, which leads to consider them as prognostic markers and targets of new therapeutic strategies." (PMID 36213817, 2022). "MMP-14 is overexpressed in a variety of diseases, including cancer." (PMID 36291022, 2022). "Moreover, exosome-transferred MMP14 led to increased cancer stemness and invasion properties in the recipient cells, which are also critical features of chemoresistance." (PMID 35223528, 2022). "The role of MMP14 in cancer development and progression has been well-established." (PMID 36428776, 2022). "In this study, MMP14 was found to be co-expressed with 47 immune checkpoint markers in cancer." (PMID 34604053, 2021). "Indeed, glioblastoma-, breast cancer-, fibrosarcoma- and melanoma-derived exosomes contain and release MMP-2 activators, such as Hsp90 (heat shock proteins (HSPs)) and/or MMP-14, that, in fine, enhance cancer cell invasion by degrading collagens." (PMID 34298680, 2021). "In the review on MMP-14 expression on cancer in general, MMP-14 was an independent prognosticator." (PMID 34344453, 2021). "To date, the immunological significance of MMP14 in cancer has rarely been reported." (PMID 34868395, 2021). "The MMP-14 was found to be highly expressed in different cancers." (PMID 35201460, 2021). "Therefore, targeting MMP14 represents a novel approach to inhibit the migration and invasion of cancer cells." (PMID 34638754, 2021). "In this study, we first analyzed MMP14 expression in generic cancer." (PMID 34604053, 2021). "Interestingly, while the MMPs members from MMP1 to MMP14 were generally upregulated in several cancer types, the others (MMP15 to MMP28) were downregulated." (PMID 34830271, 2021). "Interestingly, the fact that the EFA6BKO cells undergo EMT, display thin filopodia at the front of the leader cells, assemble MMP14 invadopodia, and sustain invasive protrusions in collagen I is reminiscent of the mechanism of invasion by cancer cells." (PMID 33850160, 2021). "While MMP-14 degrades the ECM scaffold extracellularly, this proteolytic cleavage of focal adhesion kinase (FAK) and signaling molecules by MMP-14 additionally promotes the disengaging of focal adhesions and thereby further enhances cell motility and thus the invasion of cancer cells." (PMID 35008569, 2021).
cancer (continued). "Stromal fibroblasts from MMP-14-deficient tumors do not degrade type I collagen, suggesting that cancer cell dissemination depends on TME remodeling by stromal cells." (PMID 35008569, 2021). "In addition to MMP-14, cancer cells have proteinases of the ADAMTS family, which are structurally homologous and likewise membrane-anchored, with which they also can degrade cell migration barriers." (PMID 33379400, 2020). "Furthermore, treatment with cariporide, a specific NHE1 inhibitor, was shown to decrease expression of MMP14 leading to decreased invasion of cancer cells." (PMID 32992762, 2020). "The MMP-15 amount was over 3 times higher than MMP-14 also in low-grade cancer tissues." (PMID 32049862, 2020). "MMP-14 is known as one of the key drivers of cancer invasion and progression." (PMID 32466129, 2020). "Similarly, scFv fragments developed against extracellular MMP-14 have also shown good efficacy against cancer cell invasiveness in cell line models validated in a mouse orthotopic xenograft model." (PMID 33352765, 2020). "However, it is not yet fully understood, how collagen-binding integrins regulate the expression and activity of MMP-14, and how the topography and biophysical properties of supramolecular collagen affects MMP-14-mediated cancer cell invasion." (PMID 33379400, 2020). "Interestingly, an IPA analysis showed that different regulated genes were positively associated with the invasion and migration process in cancer cells: VCAN, SPARC, IL6, MMP14, IL4R, ICAM, TIMP1 and IGF2." (PMID 32848147, 2020). "In mice, MMP-14 ablation results in delayed ossification, decreased angiogenesis, severe fibrosis, and early lethality, and MMP-14 silencing with siRNA effectively reduces cancer cell invasion as does the proteolytic removal of the MMP-14 ectodomain from its transmembrane domain." (PMID 33379400, 2020). "MMP3, MMP7, MMP12 and MMP14) are significantly up-regulated in at least 10 cancer types." (PMID 31200666, 2019). "However, similar with AID, MMP14 is also upregulated during inflammation and participates in the process of cancer progression, especially EMT36,37." (PMID 30874539, 2019). "The observed variability may be explained by the uncoupling of ECM stiffness and MMP14 activity in cancer." (PMID 31466240, 2019). "In certain cancers PROX1 appears to transcriptionally suppress MMP14 expression." (PMID 31560170, 2019). "Of these, MT1-MMP (membrane type-1 matrix metalloproteinase, MMP14) is a key protease that activates pro-MMPs such as MMP2 and MMP9 and is associated with ECM degradation and cell migration during cancer metastasis." (PMID 31223610, 2019). "MMP14 is a metalloproteinase which has been found to play a critical role in cancer invasion and metastasis by cleaving extracellular matrix and basement membrane proteins, activating proMMP-2 and -13, inducing the activation of growth factors, and enhancing cell migration." (PMID 31354524, 2019). "Moreover, leptin has been shown to induce the expression of various MMPs, such as, MMP-2, MMP-9, and membrane type 1 matrix metalloproteinase (MT1-MMP/MMP-14) in human cancer cells." (PMID 30510663, 2018). "Among the subgroups of patients with pT3–4 tumors (HR 1.74; 95% CI 1.13–2.67; p = 0.012), lymph-node metastases (HR 1.96; 95% CI 1.24–3.09; p = 0.004), or an intestinal type of cancer (HR 3.54; 95% CI 1.51–8.33; p = 0.004), a high serum MMP-14 served as a prognostic factor." (PMID 30532247, 2018). "Therefore, we tested if the PROX1-induced decrease in MMP14 affects the ability of endothelial and cancer cells to invade into 3D crosslinked fibrin." (PMID 29934628, 2018). "Fast recycling of MMP-14 also promotes invadopodia formation in cancer cells." (PMID 28938563, 2017). "Given the emergence of immune checkpoint inhibitor therapies in some cancers, it will be important to test whether MMP-14 blockade may synergize with these therapies in the future." (PMID 28938563, 2017).
cancer (continued). "Importantly, MMP2, MMP9 and MMP14 are enriched at the invadopodia and are required for cancer metastasis." (PMID 27789576, 2016). "We next examined if upregulated MMP-14 by IL-6 contributes to promoting cancer dissemination." (PMID 27531896, 2016). "Since the results shown here indicate that the loss of MMP14 catalytic activity may be the culprit in demise of new born, these findings may indeed shed some light on the failure of MMP inhibitors in clinical cancer trials." (PMID 27478693, 2016). "This seems to indicate that CD44 links MMP-14 and the actin cytoskeleton in invasive cancer cells." (PMID 27590006, 2016). "In addition to secreted MMPs, which are activated by extracellular proteolytic cleavage, hypoxia also induces the membrane bound MT1-MMP in cancer cells by direct binding of HIF-2 to an HRE in the MMP14 gene locus." (PMID 27706047, 2016). "Membrane-type 1 MMP (MT1-MMP or MMP-14), which is expressed on the cell membrane, promotes the invasion of cancer cells by directly degrading extracellular matrix components, including fibronectin, vitronectin, laminin-1 and -5, fibrin, proteoglycans and collagen types I, II and III." (PMID 24527093, 2014). "MMP-14 has been reported to be expressed by both stromal and cancer cells 22,23." (PMID 25081520, 2014). "MMP-14, a membrane-anchored matrix metalloproteinase, is closely associated with extracellular matrix (ECM) remodeling and cell migration in the progression of cancer metastasis." (PMID 24765144, 2014). "In addition, restoration of MMP-14 rescued the sub-cytotoxic MJ-induced inhibition on the migration and invasion of cancer cells, suggesting the role of MMP-14 down-regulation in the anti-metastatic activities of sub-cytotoxic MJ." (PMID 23394613, 2013). "A recent study also showed that BMP4 induces the expression of multiple MMPs, including MMP3 and MMP14, in mouse mammary fibroblasts and it also modestly induces the expression of MMP3 in cancer associated human mammary fibroblasts and to a greater degree in normal human mammary fibroblasts." (PMID 24053318, 2013). "Notably, MMP-1, MMP-2, MMP-9, and MMP-14 (MT1-MMP) have been implicated in the invasion and metastatic processes in several cancers." (PMID 20843370, 2010). "Using immunohistochemistry, MMP-14 was located within either stromal and/or cancer cells." (PMID 16776850, 2006). "In our study, MMP-14 mRNA was located in reactive stromal cells close to cancer cells." (PMID 16776850, 2006). "However, the location of MMP-14 in breast tissue is debated and others found MMP-14 mRNA in cancer cells." (PMID 16776850, 2006). "Notably, MMP14 is targeted to invadopodia in invasive cancer cells via RhoA-dependent exocytosis." (PMID 40705412, 2025). "We integrated analyzed the function of P4HA3 among 33 types of cancers, and found that P4HA3 was associated with proliferation markers (PCNA and MKI67), EMT markers (VIM, TWIST1, SNAI1, SNAI2, FN1 and CDH2), extracellular matrix (ECM) markers (MMP9, MMP7, MMP2 and MMP14)." (PMID 39504328, 2024). "Moreover, MDA‐MB‐231 cells grown in FN‐silk networks had high cancer stem cell markers (i.e., NANOG, OCT4, and SOX2), accompanied by an up‐regulation of genes associated with basement membrane degradation and invasiveness (i.e., HIF1α, ITGAV, and MMP14)." (PMID 37693069, 2023).